LEP (leptin)
Diseases named in the same sentence as LEP in open-access papers (continued):
Sharing a sentence is not in itself a finding about the gene and the disease.
asthma (continued). "Moreover, it has been demonstrated that leptin has improved cytokine production by lung fibroblasts, and MUC5AC production by IL-13 in human bronchial epithelial cells, contributing to the worsening of asthma in obese individuals." (PMID 36613991, 2022). "The cross-sectional studies manifested some findings, from high levels of leptin in overweight patients with asthma compared to normal weight patients with asthma or in asthma patients of obese compared to non-obese asthma patients to high levels of leptin related to BMI and severe lung function." (PMID 36551211, 2022). "Leptin also influences inflammatory responses by inducing the activation of monocytes and both CD4+ and CD8+ T cells, and the production of pro-inflammatory cytokines such as TNF-a or IL-18, which may affect different respiratory diseases, including asthma." (PMID 36613991, 2022). "There is no doubt that leptin plays a pro-inflammatory role in obese asthma." (PMID 36551211, 2022). "However, the role of leptin in the innate immunity-related asthma model has not yet been fully investigated." (PMID 34074279, 2021). "However, the relationship between BMI, leptin levels and asthma was not corroborated referring to the possible intervention of other factors." (PMID 32630168, 2020). "The increase in leptin is higher in obese patients with asthma than in obese ones without asthma." (PMID 31947560, 2020). "However, the expression of leptin is significantly increased in obese children and adults with asthma compared to obese patients without asthma." (PMID 33134805, 2020). "The reported increased leptin was independent of body mass index (BMI) value, thus suggesting that it may play a role in asthma independent of obesity." (PMID 30203371, 2018). "However, data supporting a role for leptin in the prevalence or severity of asthma in adult humans, independent of BMI, are inconsistent." (PMID 26770217, 2015). "It remains to be established whether modulation of leptin, independent of BMI, may be helpful in asthma prevention or treatment." (PMID 24288549, 2013). "In the present study, the serum leptin and TNF-α levels were higher in obese individuals, irrespective of the presence of asthma, suggesting that leptin might be involved in the priming of circulating eosinophils." (PMID 23773659, 2013). "Subcutaneous fat, rather than visceral fat, produces a higher amount of leptin (with greater values in females compared to males) which may be responsible for asthma worsening in obese women." (PMID 24028436, 2013). "Similarly, significant interactions between serum leptin and atopy or smoking on asthma outcomes have not been reported." (PMID 24288549, 2013). "It is indisputable that asthma is an inflammatory condition although we could not show the inflammation by using serum leptin, ghrelin and calprotectin levels in asthmatic children." (PMID 24066855, 2013). "In this study the inflammation in asthmatic children could not be shown by using serum leptin, ghrelin and calprotectin levels and this is possibly due to the low number of children with ever asthma and equal skin prick test positivity in both groups." (PMID 24066855, 2013). "We tested this hypothesis by comparing plasma cytokines, including IL-2, IL-5, IL-10, IL-13, IL-17A, IL-22, IL-33, IFN-γ, and TNF-α and the adipokine, leptin in normal weight and overweight/obese children, both with and without asthma in a cross-sectional study." (PMID 39902293, 2024). "However, there has been no research on the role of leptin in asthma among malnourished children." (PMID 37760982, 2023). "However, the conclusive effects of leptin in asthma are not well elaborated." (PMID 36551211, 2022). "A mouse study showed that leptin injection resulted in serum immunoglobulin E (IgE) and higher levels of airway AHR, but it has not been researched as a specific target in asthma." (PMID 38292857, 2023).
asthma (continued). "According to their results, leptin levels were higher in Bronchoalveolar lavage (BALF) from obese and asthma-induced animals when compared with non-obese asthmatic and non-asthmatic mice." (PMID 32630168, 2020). "We found that changes over time in either BMI-SDS, leptin and ERV% predicted were not related to changes in FEV1% predicted, FVC% predicted, or asthma control in the group as a whole." (PMID 27294869, 2016). "Although serum leptin was not correlated with airway inflammatory markers such as exhaled breath condensate-pH or exhaled nitric oxide (FeNO) levels among subjects with asthma, it was inversely correlated with FEV1/FVC ratio in the subgroup with mild/moderate asthma." (PMID 24288549, 2013).
Abdominal obesity (166 papers, 2006 to 2025). Excessive fat around the stomach and abdomen. "At the same time, abdominal obesity is associated with several hormonal imbalances, including leptin, insulin-like growth factor (IGF-1), and abnormalities in sex hormone binding globulin (SHBG)." (PMID 40129671, 2025). "In summary, our findings indicated that smoking cessation is associated with elevated leptin levels and increase in serum adiponectin levels in individuals with less abdominal obesity." (PMID 39200346, 2024). "Endocrine changes related to central obesity include dysregulation of hypothalamic–pituitary–adrenal axis and alteration of the hormone levels (e.g., cortisol, leptin, and insulin), which are implicated in the control of mood and emotion." (PMID 38418418, 2024). "Among young adults with abdominal obesity, one homozygous carrier and four heterozygous carriers of the intron variant rs17151914 of the LEP gene were identified." (PMID 37888112, 2023). "In PCOS patients, central obesity is associated with a failure of leptin signaling within the central nervous system." (PMID 34987473, 2021). "Abdominal obesity in patients is associated with higher levels of leptin and lower levels of adiponectin, which confirms their negative correlation." (PMID 34371845, 2021). "One of the important underlying factors of central obesity is leptin/adiponectin imbalance, which has been reported to be effective in determining the prognosis of diseases associated with abdominal obesity." (PMID 34262401, 2021). "Abdominal obesity is related to adipokines imbalance: increased waist circumference is associated to decreased adiponectin and increased leptin serum levels." (PMID 31947953, 2020). "A higher leptin level at baseline was associated with an increased risk of abdominal obesity and elevated BP in both men and women." (PMID 32397260, 2020). "While the increased TG/HDL-C represented central obesity, which is directly associated with insulin resistant by altering secretion of different adipocytokines namely adiponectin, leptin, resistin and visfatin." (PMID 31640743, 2019). "Central obesity is associated with an imbalance between increased leptin and reduced adiponectin, and hence the ratio between leptin and adiponectin is a sensitive marker of visceral fat related inflammatory states." (PMID 30735826, 2019). "A recent study in Korea also indicated abdominal obesity and serum leptin level were positively associated with prostate growth, whereas serum adiponectin level was negatively associated with the presence of BPH." (PMID 31426706, 2019). "Odds ratios (95% confidence interval) for the association between serum concentration of leptin and risk of frailty, by abdominal obesity and body fat (N=1,573)." (PMID 28400989, 2017). "Significantly higher levels of leptin were associated with the presence of abdominal obesity in all investigated groups, which was confirmed by a Two-way ANOVA analysis." (PMID 28421328, 2017). "We investigated the association between leptin, C‐reactive protein, and risk of cancer death while accounting general and abdominal obesity." (PMID 26632325, 2016). "Some antiretroviral medications have been linked to central obesity, which has been associated with increased inflammation related to higher leptin and lower adiponectin levels." (PMID 24884738, 2014). "Recent studies have also reported an increased risk of depressive symptoms associated with higher levels of leptin, especially in the presence of abdominal obesity." (PMID 24229349, 2013). "As is evident from our data, there is a strong relationship between leptin, adiponectin, and abdominal obesity with increased CVD risk, as assessed by the apoB/apoA1 ratio." (PMID 16606459, 2006). "Short sleep duration, on the other hand, may hyperactivate the airways by affecting eosinophil activation pathways, thereby increasing the risk of central obesity and elevated leptin levels, both of which impair lung function." (PMID 40319236, 2025).
Abdominal obesity (continued). "Thus, this study aimed to investigate the association between general and abdominal obesity and serum leptin levels among female shift workers." (PMID 41439942, 2025). "In addition to leptin resistance, abdominal obesity can cause systemic inflammation and metabolic dysfunction, leading to OSAS34." (PMID 33888816, 2021). "Furthermore, we observed that leptin had the strongest association with MetS, although the main association was observed with abdominal obesity as expected, since concentrations of leptin are correlated with total body fat." (PMID 33374992, 2020). "According to our hypotheses, central obesity is associated with upregulation in the expression of leptin, and leptin might affect autonomic function by acting both centrally and peripherally and thus leads to a decline in CAN." (PMID 33076921, 2020). "However, reduced sensitivity to leptin despite elevated levels of this hormone is often associated with abdominal obesity." (PMID 29558403, 2018). "In addition, our data revealed the interaction effect between central obesity and the clustering of the other 4 MetS risk factors on adiponectin and leptin." (PMID 30114249, 2018). "The somewhat contradictory information on the relationship between adiponectin, leptin and mortality may depend on the interaction of the risk provided by these adipokines and abdominal obesity." (PMID 28333114, 2017). "Interestingly, statistically significant differences in concentrations of leptin between all-cause dementia and controls appeared only after the stratification by abdominal obesity." (PMID 28421328, 2017). "The exacerbation in leptin level in obese patients with the clustering of 4 risk factors indicates that leptin may be involved in the severity of MetS and may lead to T2D associated with central obesity." (PMID 30114249, 2018). "Thus, abdominal obesity presumably caused leptin resistance despite smoking cessation." (PMID 30086171, 2018). "It is hypothesized that this adaptive process might cause an irreversible alteration of the regulation of certain hormonal systems (e.g., hypothalamic-pituitary-adrenal axis, leptin levels), thus leading to an increased predisposition to, especially, abdominal obesity and thus DM." (PMID 31363354, 2017). "Additionally, leptin levels are also associated both prevalent and incident central obesity and OA." (PMID 25106459, 2014). "As expected, serum levels of leptin exhibited a significant elevation in obese individuals as compared to non-obese subjects, showing a clear association with increased body mass index (r = 0.4173), central obesity (r = 0.4678), and body fat percentage (r = 0.3583)." (PMID 23986664, 2013). "Women with abdominal obesity had a mean serum leptin concentration of 45.2 ng/mL, compared with 23.8 ng/mL among those without abdominal obesity." (PMID 41439942, 2025). "Conversely, HÀ exacerbates AT dysfunction and systemic IR by altering body fat distribution (central obesity), suppressing lipogenesis, impairing lipolysis, and disrupting adipokine secretion (e.g., reduced adiponectin, elevated leptin)." (PMID 41476920, 2025). "Central obesity leads to excessive secretion of pro-inflammatory mediators like leptin, TNF-α, and IL-6, thus escalating systemic inflammation and vascular injury." (PMID 40606025, 2025). "Adipose tissue in central obesity acts not only as an energy reservoir but also as a metabolically active endocrine organ, secreting various bioactive substances, including leptin, adiponectin, and pro-inflammatory cytokines." (PMID 39834468, 2024). "Eight weeks of HFD consumption led to somatometric and metabolic changes, marked by increased body mass, central obesity, elevated plasma leptin and insulin levels, and a high HOMA–IR, reflecting key features associated with MetS." (PMID 39457000, 2024).
Abdominal obesity (continued). "Abdominal obesity is linked to the production of inflammatory cytokines and adipokines, such as TNF-α, IL-6, adiponectin and leptin, which can be involved in kidney damage." (PMID 38559695, 2024). "Our previous research stayed in line with other papers, which revealed that adiponectin levels were inversely correlated with BMI, total body fat, and the markers of abdominal obesity, whereas a positive correlation was observed for leptin and resistin levels." (PMID 37630842, 2023). "In fact, the authors showed that in patients who presented with severe coronary artery disease, the lower circulating adiponectin levels and higher leptin levels were exclusively related to abdominal obesity." (PMID 37571250, 2023). "In abdominal obesity, adipocytes generate numerous adipokines and cytokines, including leptin, adiponectin, resistin, visfatin, and chemerin." (PMID 36922815, 2023). "PCOS women with abdominal obesity were characterized by lower adiponectin concentrations but also higher leptin and resistin levels." (PMID 37630842, 2023). "A novel missense mutation Lys36Arg in exon 2 of LEP was observed in one subject with abdominal obesity and decreased serum leptin level." (PMID 36619235, 2022). "The obtained results reflect the important, perhaps main role of leptin in metabolic and lipid disorders in abdominal obesity in people under 45 years of age." (PMID 36579566, 2022). "An increase in abdominal obesity leads to a release in leptin that then leads to increased iodinase activity." (PMID 35047272, 2021). "The results of this study showed a synergistically interactive effect of leptin levels and body measurements, such as central obesity and limbs measurements, on T2DM, providing an in-depth observation of future mechanistic and preventive methods." (PMID 34368053, 2021). "In patients with severe coronary artery disease, abdominal obesity is commonly related to increased leptin concentrations and decreased adiponectin concentrations." (PMID 34446063, 2021). "The coexistence of poor cardiovascular function, higher leptin level, and central obesity is demonstrated in patients with T2DM and prediabetes." (PMID 33076921, 2020). "Central obesity, systolic blood pressure, lipid profile, glucose hemostasis and levels of leptin and adiponectin were evaluated." (PMID 32559253, 2020). "A single-level three-variable mediation model was used to investigate the possible relationships among central obesity [as indicated by waist circumference (WC)], leptin level, and severity of CAN (as indicated by CASS value)." (PMID 33076921, 2020). "Body weight and central obesity are controlled by several hormones and molecules including adipokines; leptin and adiponectin." (PMID 32559253, 2020). "To date, there is a paucity of information that focuses on the relationship among central obesity, leptin level and severity of CAN in patients withT2DM." (PMID 33076921, 2020). "As the leptin level serves as mediator between central obesity and severity of CAN, a longitudinal study is needed to confirm that control of WC can decrease leptin levels and can be effective in reducing CAN progression." (PMID 33076921, 2020). "In conclusion, our results revealed the interaction of central obesity and the clustering of the other MetS cardiometabolic risk factors for exacerbating circulatory TNF-α and leptin; and reducing adiponectin." (PMID 30114249, 2018). "Our results indicated that the interaction effects between central obesity and the clustering of other 4 MetS cardiometabolic risk factors existed for TNF-α, adiponectin and leptin." (PMID 30114249, 2018). "The interacting effect of central obesity with all of the other four MetS risk factors increased the proinflammatory status of adipokines (TNF-α, leptin) and decreased the anti-inflammatory status of adipokine (adiponectin)." (PMID 30114249, 2018).